IFT172 (intraflagellar transport 172)
Description:
Required for the maintenance and formation of cilia. Plays an indirect role in hedgehog (Hh) signaling, cilia being required for all activity of the hedgehog pathway (By similarity).
Synonyms: SLB; wim; osm-1; NPHP17; BBS20; RP71; SRTD10
Tractability: PROTAC: UniProt records ubiquitination sites on it; ubiquitination databases record sites on it.
Gene: Protein-coding gene on chromosome 2 (27,444,377 to 27,489,836, reverse strand). Ensembl gene ENSG00000138002.
Subcellular location: Cell projection, cilium
Pathways (Reactome):
Organelle biogenesis and maintenance: Intraflagellar transport
Signal Transduction: Hedgehog 'off' state
Gene Ontology:
Molecular function: protein binding
Biological process: cilium assembly; intraciliary anterograde transport; intraciliary transport; cilium organization; smoothened signaling pathway
Cellular component: extracellular vesicle; intraciliary transport particle A; intraciliary transport particle B; axoneme; ciliary basal body; ciliary tip; cilium; intraciliary transport particle; sperm cytoplasmic droplet; sperm midpiece; sperm principal piece
Genetic constraint (gnomAD): Loss-of-function variants: 144 observed, 222.04 expected, observed/expected ratio (o/e) 0.65, 90% interval 0.56 to 0.75. The upper end of that interval is the gene's LOEUF score, 0.75, which puts it in group 3 of 6, group 1 being the genes least tolerant of losing a copy. Missense variants: 1,706 observed, 2,040.5 expected, observed/expected ratio (o/e) 0.84, 90% interval 0.8 to 0.87. Synonymous variants: 652 observed, 748.95 expected, observed/expected ratio (o/e) 0.87, 90% interval 0.82 to 0.93.
Gene-disease validity (ClinGen):
ClinGen rates the evidence that IFT172 causes each of these diseases.
ciliopathy (autosomal recessive): Definitive. A genetic disorder of the cellular cilia or the cilia anchoring structures, the basal bodies, or of ciliary function.
Homologues: Orthologues: macaque IFT172 (99% identical), chimpanzee IFT172 (99% identical), rat Ift172 (96% identical), mouse Ift172 (96% identical), rabbit IFT172 (95% identical), dog IFT172 (95% identical), guinea pig IFT172 (94% identical), pig IFT172 (94% identical), zebrafish ift172 (75% identical), tropical clawed frog ift172 (75% identical), Drosophila melanogaster Oseg2 (47% identical), Caenorhabditis elegans osm-1 (42% identical). Paralogues in human: IFT140 (16% identical).
Diseases named in the same sentence as IFT172 in open-access papers:
IFT172 is named in the same sentence as 56 diseases in open-access papers, as found by Europe PMC text mining. Sharing a sentence is not in itself a finding about the gene and the disease. The quoted sentences say what the papers report.
ciliopathies (14 papers, 2017 to 2025). "We also examine the cilia-associated signaling pathways, particularly the role of IFT172 and candidate ciliopathy genes." (PMID 40692799, 2025). "Further, the VACTERL mimicking Intraflagellar Transport 172 (Ift172)avc1 mutant mice, showed an association with ciliopathies." (PMID 37238430, 2023). "IFT172 mutation has been considered a new cause of anosmia and can be used as a novel diagnostic index of ciliopathies." (PMID 36733456, 2023). "Mutations in human ift172 cause Jeune and Mainzer-Saldino syndromes, ciliopathies characterised by skeletal, renal, hepatic, or retinal abnormalities." (PMID 30875791, 2019). "Our results highlight ift172-deficiency as a novel cause of hyposmia and support the idea that hyposmia can be used as a diagnostic indicator of ciliopathies." (PMID 29568513, 2018). "A possible involvement of ciliopathies in EA development is suggested by animal models, specifically, esophageal and tracheal anomalies were observed in a ciliopathy-associated mouse model with an Ift172 hypomorphic variant." (PMID 40428346, 2025). "As the largest structural component of the IFT-B protein complex, IFT172 is involved in anterograde transportation and thus frequently engaged in diseases including related ciliopathies, growth hormone deficiency, non-syndromic retinitis pigmentosa, MKS, and Mainzer-Saldino syndrome (MZSDS)." (PMID 36733456, 2023). "Our results also implicate ift172-deficiency as a novel cause of hyposmia, a reduced sense of smell, highlighting the value of directly assaying sensory cilia signalling in vivo and supporting the idea that hyposmia can be used as a diagnostic indicator of ciliopathies." (PMID 29568513, 2018). "The study found that SPAG6, TRAF3IP1, IFT22, and KIF3B showed lower correlations with ciliopathies, while IFT172, TTC21B, CEP290, ACTB, and DYNC1H1 were highly correlated." (PMID 40432967, 2025). "This review mainly focuses on the key findings on the genetic and protein characteristic of IFT172, as well as its function in intraflagellar transport, to provide comprehensive insights to understand IFT172-related ciliopathies." (PMID 36733456, 2023). "Intraflagellar transport 172 (IFT172) is a newly identified member of IFT proteins closely involved in some rare ciliopathies such as Mainzer-Saldino syndrome (MZSDS) and BBS, though the underpinning causal mechanisms remain largely elusive." (PMID 36733456, 2023). "The present study reports four prenatal cases of SRPS/SRTD as implicated by ultrasound findings, which provide useful information regarding the novel variants of ciliopathies-associated genes DYNC2H1, IFT172, and WDR19." (PMID 38062428, 2023). "In this review, we summarize the key findings on the genetic and protein characteristic of IFT172, as well as its function in intraflagellar transport, to provide comprehensive insights to understand IFT172-related ciliopathies." (PMID 36733456, 2023). "MZSDS was first classified as a ciliopathy when recessive mutations in IFT140 were reported to be causative, and it is now known also to be caused by dysfunction of IFT172." (PMID 28724397, 2017). "Collectively, our case series provide information regarding the novel variants of ciliopathies-associated genes DYNC2H1, IFT172, and WDR19, and emphasize the importance of both clinical and genetic findings in the setting of prenatal diagnosis for skeletal disorders." (PMID 38062428, 2023). "WES revealed biallelic variation in 3 ciliopathy genes (PKHD1, TMEM67 and IFT172) in 4 clinically unrelated index subjects (3 children and 1 adult), heterozygosity for a known variant in PPOX in one adult index subject, and homozygosity for an unreported splice-site variation in F11R in one child." (PMID 37471416, 2023). "However, neither of these two ciliopathies is caused exclusively by IFT-A dysfunction; for example, JATD can be caused by mutations in the anterograde IFT genes (complex B) IFT80 or IFT172." (PMID 28724397, 2017).
Bardet-Biedl syndrome (5 papers, 2018 to 2025). A ciliopathy with multisystem involvement. "In humans, IFT172 mutations cause isolated retinal degeneration, Jeune, Mainzer-Saldino and Bardet–Biedl syndromes." (PMID 29568513, 2018). "Indeed, pathogenic IFT172 variants have been reported in syndromic conditions such as Mainzer–Saldino and Bardet–Biedl syndromes, which can include clefting and renal malformations as part of the clinical spectrum." (PMID 41465536, 2025). "IFT172 is a member of the IFT complex B, and IFT172 mutation is associated with pathologies including short rib thoracic dysplasia, retinitis pigmentosa and Bardet-Biedl syndrome, but how it underpins these conditions is not clear." (PMID 31850339, 2019). "The finding of a homozygous c.167A>C p.(Lys56Thr) “warm” VUS in IFT172 suggested short-rib thoracic dysplasia 10 (SRTD10, OMIM #615630) or Bardet-Biedl syndrome 20 (OMIM #619471)." (PMID 37471416, 2023).
short-rib thoracic dysplasia (5 papers, 2015 to 2023). "In a previous study, homozygous or compound heterozygous mutations in IFT172 were detected in 12 families with affected individuals diagnosed with asphyxiating thoracic dystrophy (ATD; also known as Jeune syndrome) or Mainzer-Saldino syndrome (MZSDS)." (PMID 38062428, 2023). "Being a component of the IFT complex B and of the BBSome, human IFT172 deficiency can cause several discrete conditions, such as short rib thoracic dysplasia, retinitis pigmentosa, and BBS." (PMID 31850339, 2019). "Mutations in IFT172 are known to cause retinitis pigmentosa (OMIM: #616394) or short-rib thoracic dysplasia (OMIM: # 615630); the latter might be also be partially correlated with the fetal phenotype but might only present in later gestation." (PMID 31475041, 2019). "In humans, IFT172 mutation is associated with short-rib thoracic dysplasia (a skeletal ciliopathy) with or without polydactyly." (PMID 31850339, 2019). "The genotypes of DYNC2H1, IFT172 and WDR19 and the phenotypes of the fetuses give hints for the diagnosis of short-rib thoracic dysplasia (SRTD) with or without polydactyly 3, 10, and 5, respectively." (PMID 38062428, 2023).
retinal degeneration (4 papers, 2018 to 2025). Degeneration of the retina. "Among 260 conserved genes between ift88−/− versus ift88+/+ and ift172−/− versus ift172+/+at 5 dpf (these mutants had the strongest retinal degeneration), we defined 65 retinal-associated differentially expressed genes (DEGs)." (PMID 36533556, 2022). "A variety of genes involved in IFT, such as Ift88, Ift122, Ift81, Ift172, and Ift52, have been reported to be associated with retinal degeneration." (PMID 36171205, 2022). "Stx3 accumulates in the outer segment in models of retinal degeneration caused by defects in the BBSome, but not in Ift20 and Ift172 knockouts." (PMID 39871753, 2025).
retinitis pigmentosa (4 papers, 2019 to 2023). Retinitis pigmentosa (RP) is an inherited retinal dystrophy leading to progressive loss of the photoreceptors and retinal pigment epithelium and resulting in blindness usually after several decades. "The IFT172 gene has been associated with autosomal recessive Bardet-Biedl syndrome, non-syndromic retinitis pigmentosa and SRTD10." (PMID 38062428, 2023). "Nor did ophthalmologic examination identify retinitis pigmentosa, typical in IFT172 deficiency." (PMID 37471416, 2023).
Bardet-Biedl syndrome type 20 (2 papers, 2021 to 2024). "IFT172 variants have been associated with CH and Bardet-Biedl syndrome type 20, and TMEM67 variants have been associated with CH and Meckel/Joubert syndrome, and there is significant genetic overlap between these syndromes and Bardet-Biedl." (PMID 38822427, 2024).
cyst (2 papers, 2019 to 2021). A sac-like closed membranous structure that may be empty or contain fluid or amorphous material. "The smart imaging screening pipeline was used to profile 1280 approved drugs for modifiers of cyst formation in the Ift172 knockdown model (Pandey, manuscript in preparation)." (PMID 30875791, 2019). "A histone deacetylase (HDAC) inhibitor was identified that suppressed cyst formation in pkd2- but not in ift172-morphants, making this finding less relevant for NPH." (PMID 34055783, 2021). "In addition, an automated imaging pipeline was recently developed to efficiently profile a large compound library in ift172-morphant zebrafish embryos, however, identified pronephric cyst-modifying compounds were not reported." (PMID 34055783, 2021).
Hydrocephalus (2 papers, 2018 to 2023). Hydrocephalus is an active distension of the ventricular system of the brain resulting from inadequate passage of CSF from its point of production within the cerebral ventricles to its point of absorption into the systemic circulation. "Both mice and zebrafish animal models carrying an Ift172 mutation displayed hydrocephalus." (PMID 36859317, 2023). "Indeed, a recessive N-ethyl,N-nitrosurea (ENU)-induced hypomorphic mutation in Ift172 in mice caused VACTERL syndrome associated with hydrocephalus, and an ift172 knockdown zebrafish model displayed anomalies including ventral body curvature and hydrocephalus." (PMID 36859317, 2023). "ift172 morphants phenocopied ift172 mutants with ventral axis curvature, hydrocephalus and kidney cysts." (PMID 29568513, 2018).
male infertility (2 papers, 2022 to 2023). The inability of the male to effect fertilization of an ovum after a specified period of unprotected intercourse. "Additionally, deficiency in IFT74, IFT81, IFT140, and IFT172 have been proven to be related to spermiogenesis defects and male infertility." (PMID 36321563, 2022). "Mutations in other IFT-B gene additional to IFT74 (IFT81, IFT20, IFT27, IFT172), and in IFT-A genes (IFT140) can cause spermatogenesis defects and male infertility in mice." (PMID 37555648, 2023).
cystic kidney (1 paper, 2019). "In the Ift172 screen, two basic phenotypes were observed: (i) pronephros resembling the wild-type phenotype and (ii) the cystic kidney phenotype." (PMID 30875791, 2019).
cystic kidney disease (1 paper, 2019). A congenital or acquired kidney disorder characterized by the presence of renal cysts. "We exploited this to generate a zebrafish model for cystic kidney disease using splice-morpholinos-based knockdown of Ift172 in the Tg(wt1b:EGFP) transgenic line, resulting in readily scorable glomerular cysts." (PMID 30875791, 2019). "For this study, a morpholino oligonucleotide-based knockdown of the ift172 gene was utilised to mimic the human cystic kidney disease phenotype in embryos of the Tg(wt1b:EGFP) transgenic line." (PMID 30875791, 2019).
glaucoma (1 paper, 2021). Increased pressure in the eyeball due to obstruction of the outflow of aqueous humor. "Other variants in genes for IFT172, DFNB31, PDHX, SALL2, BMP4 and GPR179 by WES were excluded as deleterious and pathogenic mutations, and none of them was reported as a stronger/convincing glaucoma causing variant in the literature." (PMID 34399712, 2021).
hypertriglyceridemia (1 paper, 2023). A laboratory test result indicating elevated triglyceride concentration in the blood. "We newly identified the IFT172/NRBP1 region, in the literature previously associated with hypertriglyceridemia, as involved in apolipoprotein-CIII sialylation and hypertriglyceridemia." (PMID 37834292, 2023).
Infertility (1 paper, 2021). "The IFT172 (hypermethylated in our study) has been related to defects in spermiogenesis and infertility of male mice." (PMID 33800945, 2021).
Metaphyseal dysplasia (1 paper, 2020). The presence of dysplastic regions in metaphyseal regions. "Recently, mutation in IFT172 has been associated with a phenotype characterized by anterior pituitary hypoplasia, an ectopic posterior pituitary, retinopathy, metaphyseal dysplasia, and renal failure." (PMID 32060556, 2020).
respiratory failure (1 paper, 2015). The significant impairment of gas exchange within the lungs resulting in hypoxia, hypercarbia, or both, to the extent that organ tissue perfusion is severely compromised. "Furthermore, all affected individuals died from respiratory failure and a severe short rib phenotype which is not observed in individuals with IFT140, IFT172 or IFT80 mutations." (PMID 25361962, 2015).
cancer (2 papers, 2016 to 2021). A tumor composed of atypical neoplastic, often pleomorphic cells that invade other tissues. "We also found GIST to highly express four genes (KIF3A, IFT52, IFT88, and IFT172), which are associated with PC function in several cancers." (PMID 27793025, 2016).
retinopathy (2 papers, 2019 to 2020). "Intriguingly, recapitulation of Ift172 mutation or conditional Ift172 knockout could lead to similar retinopathy in mice." (PMID 31850339, 2019).
skeletal dysplasia (2 papers, 2021). Any Mendelian diseases that affects growth and development of the skeleton. "Almost 20 ciliary genes are associated with skeletal dysplasias, and biallelic variants in other ciliary genes (ALMS1, IFT172, and KIAA0753) have been discovered in individuals with growth hormone deficiency." (PMID 34194391, 2021).
mental illness (1 paper, 2019). "Notably, the spatiotemporal expression pattern of Ift172 is similar to that of Ulk4, a rare risk factor we uncovered recently which is implicated in neocortical development and mental illness." (PMID 31850339, 2019).
nephropathy (1 paper, 2023). A nonspecific term referring to disease or damage of the kidneys. "Defects to the IFT-A complex of proteins (e.g., WDR35, IFT122, IFT43, IFT172, IFT140 and WDR19), can present with renal disease phenotypes such as chronic renal failure, NPHP, and renal cysts and, in some cases, isolated NPHP or NPHP-like nephropathy." (PMID 38292052, 2023).
neurodevelopmental disorder (1 paper, 2019). A behavioral and cognitive disorder with onset during the developmental period that involves impaired or aberrant development of intellectual, motor, or social functions. "Our in vitro data and findings implicating IFT172 in neurodevelopmental disorders, prompted us to investigate the in vivo roles of Ift172 during corticogenesis." (PMID 31850339, 2019). "Yet, further study is necessary to elucidate both the extent of ciliary role in particular neurodevelopmental disorders, as well as the impact of IFT172 function in human patients." (PMID 31850339, 2019).
IFT172 also shares sentences with these, for which no sentence is quoted: infection (3 papers); Mainzer-Saldino syndrome (2); basal cell carcinoma (1); Crohn disease (1); Dent disease (1); depression (1); developmental delay (1); dyslipidemia (1); endometriosis (1); epilepsy (1); Epileptic encephalopathy (1); Fabry disease (1); fibrosis (1); genetic disease (1); Hyperglycemia (1); hypertrophic cardiomyopathy (1); intracranial hemorrhage (1); Joubert syndrome (1); Kidney Cyst (1); Leber congenital amaurosis (1); Lowe syndrome (1); Methylmalonic aciduria (1); nephronophthisis (1); Obesity (1); orofacial cleft (1); orofaciodigital syndrome (1); polydactyly (1); renal failure (1); retinal diseases (1); Retinal dystrophy (1).
A further 4 diseases each share a sentence with IFT172 in 1 paper.